SOD2 (superoxide dismutase 2)
Diseases named in the same sentence as SOD2 in open-access papers (continued):
Sharing a sentence is not in itself a finding about the gene and the disease.
atherosclerosis (continued). "For example, overexpression of SIRT3 can deacetylate and activate superoxide dismutase 2 (SOD2) to reduce intracellular reactive oxygen species (ROS), which in turn improves atherosclerosis." (PMID 32139662, 2020). "Moreover genes encoding for a variety of proteins that have been associated with atherosclerosis were up-regulated including phospholipase A2 (PLA2G4C), prostaglandin synthase 2 (PTGS2) also known as cyclooxygenase-2, thrombin receptor like-1 and the gene encoding for superoxide dismutase 2 (SOD2)." (PMID 17534423, 2007). "Aberrant methylation of genes like SOD2 and FGF2 contributing to atherosclerosis in T2DM." (PMID 38323108, 2024). "In conclusion, genetically modified mice overexpressing Cat, Cat+SOD1, PRDX4, or Trx2 in ECs and the deletion of scavenger systems such as the nuclear factor [erythroid-derived 2]-like 2 related factors 2 (Nrf-2), GPX1, SOD2, and PRDX1 and 2 indicate a protective role in atherosclerosis." (PMID 35883899, 2022). "The expected effect was to observe a greater expression of SOD2 in atherosclerotic plaques than in control aortic fragments without signs of atherosclerosis." (PMID 34202347, 2021). "Of particular interest, pathway enrichment analysis of the 34 common gene associated DMRs revealed epigenetic impairment of NRF2 oxidative stress (SOD2), DNA repair (BRCA1), thioredoxin (TXNRD1) and inflammatory pathways (MIF, PLA2G4D) in atherosclerosis conditions." (PMID 28698603, 2017). "Several of the differentially regulated genes are involved in vascular pathophysiology; for example: DNAJB6 and DUSP1 (atherosclerosis), NAMPT (vascular inflammation), FCAR (myocardial infarction), IL8 (vascular remodelling), FFAR2 (lipid metabolism) and SOD2 (idiopathic cardiomyopathy (IDC))." (PMID 22409835, 2012). "IL6, CXCL8, CCL2, SOD2, NFKBIA, and BIRC3 were identified as the top 6 hub genes in the magenta module (human cardiomyocyte samples) and were mainly enriched in the NOD-like receptor signaling pathway, IL-17 signaling pathway, TNF signaling pathway, lipid and atherosclerosis signaling pathway." (PMID 36426222, 2022).
cardiac hypertrophy (42 papers, 2011 to 2025). "Heart weight to tibia length ration showed the relative myocardial hypertrophy after deficiency of SOD2." (PMID 31915037, 2020). "Interestingly, mice subjected to transverse aortic constriction (TAC) surgery for 4 weeks developed cardiac hypertrophy and fibrosis associated with an increase in oxidative stress related to decreased SOD2 activity and SIRT3 expression." (PMID 35453408, 2022). "Interestingly, these mice showed dilated cardiomyopathy as well as increased ROS production and mitochondrial dysfunction, confirming the association between SOD2 inactivation, ROS production and cardiac hypertrophy." (PMID 35453408, 2022). "Hence, we focused on the Sirt3/SOD2 signaling pathway in order to elucidate the possible mechanisms underlying the inhibitory effects of SA against cardiac hypertrophy." (PMID 33233476, 2020). "SOD2 is an essential antioxidative enzyme scavenging ROS and protecting mitochondria; mice with reduced SOD2 activity develop heart hypertrophy and display an increase in left ventricular volume in systole." (PMID 37228086, 2023). "We also confirmed that both forkhead box protein 3a (FOXO3a) and SOD2 are down-stream targets to regulate mitochondrial function and oxidative stress in myocardial hypertrophy." (PMID 36671063, 2023). "Sirt3 inhibited cardiac hypertrophy by stimulating the Forkhead box O3a-dependent (Foxo3a-dependent), manganese superoxide dismutase (MnSOD) or superoxide dismutase 2 (SOD2) and catalase (Cat), thus suppressing cellular levels of ROS in primary cardiomyocytes." (PMID 35052850, 2022). "It was found that SIRT3 activates SOD2 and catalase to block cardiac hypertrophy in primary cardiomyocytes cultures, thereby decreasing ROS levels." (PMID 35571098, 2022). "Sirt3, a mitochondrial deacetylase enzyme, has a preventive effect against cardiac hypertrophy through regulating the mitochondrial function by the deacetylation of mitochondrial proteins, particularly SOD2." (PMID 33233476, 2020). "Taken together, our results demonstrate that REGγ regulates SOD2 expression in a PP2Acα–FoxO3a axis-dependent manner in response to hypertrophic stimuli, and may de on it in the regulation of oxidative stress and cardiac hypertrophy." (PMID 32424140, 2020). "Our data showed that REGγ knockout protect against TAC or Ang II-induced SOD2 decline by targeting PP2Acα for degradation, indicated REGγ maybe the key factor in the improvement of PP2Acα-oxidative stress induced pathological cardiac hypertrophy." (PMID 32424140, 2020). "In response to hypertrophic stimuli, REGγ is significantly increased and targets PP2Acα for degradation, which leads to increase of FoxO3a phosphorylation and nuclear export, and subsequent cardiac SOD2 decline and ROS accumulation, thus results in cardiac hypertrophy." (PMID 32424140, 2020). "Mechanistically, REGγ interacted with and targeted PP2Acα for degradation directly, thereby leading to increase of phosphorylation levels and nuclear export of Forkhead box protein O (FoxO) 3a and subsequent of SOD2 decline, ROS accumulation, and cardiac hypertrophy." (PMID 32424140, 2020). "Furthermore, DHY pretreatment decreased myocardial ROS production and MDA level, while increased T-AOC, SOD activity and SOD2 expression to ameliorate transverse aortic constriction (TAC) induced myocardial hypertrophy." (PMID 32933152, 2020). "We investigated the role of SOD2 during cardiac hypertrophy in H9c2 cells." (PMID 29116107, 2017). "SIRT3 deacetylates/activates superoxide dismutase 2 (SOD2) which further increases the deacetylation of transcription factor forkhead box o3a (FOXO 3a) and protects against cardiac hypertrophy." (PMID 28197299, 2017).
ovarian carcinoma (42 papers, 2006 to 2025). A malignant neoplasm originating from the surface ovarian epithelium. "In contrast to SOD1, SOD2 expression is upregulated in cancer cells and ovarian cancer cells associated with endometriosis." (PMID 37968795, 2024). "So far, previous research has indicated a significant impact of SOD2 polymorphism (rs4880) on the increased risk for breast, lung, prostate, colon and ovarian cancer development." (PMID 35205816, 2022). "There is growing evidence that SOD2 overexpression is associated with poor prognosis in a variety of cancer types, including renal clear cell carcinoma and ovarian cancer 354-356." (PMID 34093804, 2021). "A study based on SOD2 immunohistochemical staining confirmed the correlation between SOD2 expression and patient prognosis in the endometriosis-associated ovarian cancer (EAOC) case group." (PMID 34093804, 2021). "For example, elevated SOD2 expression was identified as a major protein change in fibroblasts associated with ovarian cancer cells." (PMID 29099803, 2017). "Similarly, in ovarian cancer cells, SOD2 protein expression is associated with increased oxidative stress, and ovarian cancer cells rapidly increase their mitochondrial antioxidant capacity through this mechanism as a means to adapt to the loss of anchor points and escape anoikis." (PMID 36291283, 2022). "Since our data demonstrated that oxidative stress was lower in PBMCs from the participants with ovarian cancer, antioxidants, SOD2 and GPX4, were investigated as indicators of the mechanism responsible for a reduction in oxidative stress." (PMID 38168673, 2024). "Dual role of SOD2 expression has been suggested in ovarian cancer as tumor suppressor and protumoregenic factor; therefore, antioxidant capacity of HGSOC need to be critically evaluated in future studies." (PMID 36937395, 2023). "Several foregoing researches have illuminated SOD2 as augmented by epithelial ovarian cancer (EOC) tissues and cells, accelerating EOC cell advancement with chemical sensitivity." (PMID 35543376, 2022). "For example, FOXO1 is overexpressed in paclitaxel-resistant ovarian cancer cells, which can protect these ovarian cancer cells from oxidative stress-induced apoptosis through regulation of superoxide dismutase 2 (SOD2)." (PMID 34123834, 2021). "The cancer genome atlas (TCGA) database cannot suggest that SOD2 is a prognostic indicator in ovarian cancer." (PMID 30700285, 2019). "Suppression of SOD2 enhances ROS production in ovarian cancer cells and results in increased apoptosis, inhibition of proliferation, and enhanced sensitivity to chemotherapy." (PMID 30700285, 2019). "In parallel, GPX4 expression positively correlated with elevated ALDH1A1 levels in colon CSCs 53, and fluorescence-activated cell sorting (FACS) analysis revealed that SOD2 was upregulated in ALDH+ ovarian cancer cells." (PMID 31695757, 2019). "We demonstrated that SOD2 has a pro-metastatic role and is specifically elevated in ovarian clear cell carcinomas compared to other ovarian cancer subtypes." (PMID 29099803, 2017). "SOD2 Val-9Ala polymorphism, which results in more efficient importation of the MnSOD enzyme, seems to increase prostate and cervical cancer risk while not affecting ovarian cancer risk or survival." (PMID 39040459, 2024). "The assumption that persistent oxidative stress and chronic low-grade inflammation are predisposing factors for the development of polycystic ovarian condition and the subsequent development of ovarian cancer is based on the observation of an increased expression of SOD2 by the hen ovaries." (PMID 30596106, 2018). "SOD2 may promote the progression of ovarian cancer; thus, it is suggested that inhibiting the expression of SOD2 may hinder the development and invasion of ovarian cancer by increasing the level of ROS that oxidatively damages ovarian cancer cells." (PMID 39857448, 2025).
ovarian carcinoma (continued). "Within ovarian cancer, the protective role of hsa-miR-146a-5p may be explained in part by its effect on superoxide dismutase 2 (SOD2), which leads to increased levels of reactive oxygen species (ROS), decreased proliferation, increased apoptosis, and enhanced sensitivity to chemotherapy." (PMID 34067485, 2021). "In epithelial ovarian cancer, SIRT3 prevents mitochondrial superoxide surges to promote cell survival by increasing the activity of the manganese superoxide dismutase (SOD2) in detached cancer cells during the metastatic process." (PMID 40777993, 2025). "In contrast, activation of SIRT3, which regulates manganese superoxide dismutase (SOD2), is essential for anchorage-independent survival and metastasis of ovarian cancer cells." (PMID 37446063, 2023). "On the other hand, the ovarian cancer cell lines with reduced OXPHOS subunit expression and mitochondrial translation generated the highest levels of mtROS and significantly reduced SOD2 expression." (PMID 36937395, 2023). "Some studies further demonstrated a significantly increased expression of CuZnSOD (SOD1), MnSOD (SOD2), and catalase in chronic lymphocytic leukemia cells and ovarian cancer cells." (PMID 23431283, 2013). "The decreased SOD2 levels or antioxidant capacity of ovarian cancer cells with low-OXPHOS, such as OVCAR-8, is not sufficient to scavenge mtROS generated in these cells." (PMID 36937395, 2023). "However, in ovarian cancer, especially in EAOC, the correlation between SOD2 expression and prognosis remains unknown." (PMID 30700285, 2019).
pancreatic cancer (42 papers, 2007 to 2025). "Our findings provide key insights into the association between low SOD2 expression and a survival advantage in two pancreatic cancer cohorts (TCGA, ICGC)." (PMID 41353397, 2025). "To investigate the effects of Sod2 loss, we selected three independent KrasG12D mutant pancreatic cancer cell lines previously isolated from genetically engineered KC mice." (PMID 41353397, 2025). "The A allele of the SOD2 − 1221G > A genotype was associated with a higher risk of pancreatic cancer among individuals with a low dietary vitamin E intake." (PMID 26439801, 2015). "Conversely, reduction of SOD2 abundance causes increased EFhd1 expression in a human pancreatic carcinoma cell line (MIA-PaCa2)." (PMID 21244694, 2011). "The epigenetic silencing of sod2 revealed a particular Achille's heel of pancreatic carcinoma cells with low SOD2, making the cells particularly susceptible to the apoptotic effects of 2-methoxyestradiol (2ME2), an oxidative burst agent." (PMID 17895890, 2007). "Overexpression of SOD2 in deficient cell lines has reduced the proliferation of pancreatic carcinoma cells, multiple myeloma cells, glioma cells, squamous oral carcinoma cells, and prostate carcinoma cells." (PMID 17895890, 2007). "SOD2 is involved in oxidative phosphorylation and the regulation of ROS (reactive oxygen species), and upregulation in its expression has been linked with acquired resistance to ROS-inducing anticancer drugs and potential irradiation in pancreatic cancer cell lines." (PMID 36983764, 2023). "To elucidate the role of TET in stimulating ROS production in pancreatic cancer subcutaneous tumors, we further performed IHC staining of SOD2 and DHE staining on the subcutaneous tumors." (PMID 38987818, 2024). "IHC staining of SOD2 indicated that treatment of TET led to an increased expression of SOD2 in pancreatic cancer, suggesting an elevated level of oxidative stress in the cells." (PMID 38987818, 2024). "In silico analysis was performed to identify the prognostic value of SOD2 in pancreatic cancer patients using the Kaplan–Meier plot." (PMID 37891871, 2023). "Together, our data show that NB inhibits SOD2 and increases ROS to inhibit proliferation, migration, invasion, and colony formation in pancreatic cancer cells." (PMID 37891871, 2023). "Silencing SOD2 diminished the proliferative capacity of pancreatic cancer cells, which was further reduced by NB treatment." (PMID 37891871, 2023). "Our data demonstrate that an elevated expression level of SOD2 positively correlates with increasing tumor grade and decreased overall survival and recurrence-free survival time in pancreatic cancer patients." (PMID 37891871, 2023). "All these data suggest that NB inhibits pancreatic cancer growth by altering SOD2 levels, resulting in the generation of excessive ROS." (PMID 37891871, 2023). "Through IHC analysis we found that SOD2 isoform is overexpressed in human pancreatic tumor tissues and pancreatic cancer cell lines, and SOD2 has a higher expression than other isoforms of SOD." (PMID 37891871, 2023). "HPAC cells were selected for further experiments to study the role of SOD2 in NB’s anticancer effect against pancreatic cancer." (PMID 37891871, 2023). "Previous studies have reported the capability of SOD2 to induce EMT via the production of H2O2 in pancreatic cancer cells." (PMID 33535682, 2021). "Using the four pancreatic carcinoma cell lines with variable SOD2 expression, we examined 2ME2 sensitivity in an MTT assay." (PMID 17895890, 2007). "In particular, we were interested in the effects that the manipulation of SOD2 expression levels has in pancreatic carcinoma cell lines, since they have decreased expression of SOD2 resulting in increased proliferation rates." (PMID 17895890, 2007).
pancreatic cancer (continued). "Using reverse-phase antibody arrays for signal proteins, transcription factor arrays and gene expression microarrays, we have identified some of the major aspects in which SOD2 governs signal transduction and gene expression in pancreatic carcinoma cells." (PMID 17895890, 2007). "Here, using a series of pancreatic carcinoma cell lines, we show that the relative expression patterns of SOD2 are inversely related to the methylation density status of the sod2 promoter." (PMID 17895890, 2007). "The role of hypermethylation in the silencing of sod2 in primary pancreatic carcinoma needs to be determined, but our initial studies using the pancreatic carcinoma cell lines indicate a possible role for hypermethylation." (PMID 17895890, 2007). "Similarly, SOD2 was significantly upregulated by the kinase Mirk/Dyrk1B in quiescent pancreatic cancer cells." (PMID 40520023, 2025). "Notably, among these genes, SOD2, P4HB, and TNFSF10 were identified as hub genes associated with adverse prognostic outcomes in pancreatic cancer." (PMID 38685045, 2024). "In present study SOD2 has found to be downregulated, one of previous study has demonstrating the similar findings as it has been reported that SOD2 showed downregulated expression in breast, esophageal and pancreatic cancers." (PMID 36809279, 2023). "Immunohistochemical analysis was conducted to explore the pathophysiological relationship between PDAC stage and SOD2 levels, using a pancreatic cancer tissue microarray, which consisted of different grades of pancreatic cancer and also normal pancreatic tissues." (PMID 37891871, 2023). "Furthermore, SOD2 expression increased proportionately with the increasing grade of pancreatic cancers, demonstrating a positive correlation between pancreatic cancer progression and SOD2 expression." (PMID 37891871, 2023). "In this study, we aimed to understand the role of SOD2 in pancreatic cancer." (PMID 37891871, 2023). "Our data indicate that SOD2 acts as a tumor promotor in pancreatic cancer patients." (PMID 37891871, 2023). "Considering other types of cancer, the SOD2 protein concentration and gene expression in esophageal cancer tissue were found to be decreased compared to in normal tissue, and pancreatic cancer cell lines had lower levels of SOD2 than normal human pancreas cells." (PMID 34832849, 2021). "In pancreatic cancer, overexpression of reactive oxygen species (ROS)-detoxifying genes superoxide dismutase 2 (SOD2) and catalase (CAT) and downregulation of gemcitabine-metabolizing enzyme deoxycytidine kinase (DCK) confers cellular chemoresistance through exosome-derived miRNA-155." (PMID 33396739, 2020). "Interestingly, ectopic expression of manganese superoxide dismutase 2 (SOD2), a mitochondrial enzyme that inactivates superoxide to protect cells from oxidative damage, induces down-regulation of EFhd1 in a pancreatic carcinoma cell line." (PMID 21244694, 2011). "We have begun to understand the molecular consequences of altered SOD2 activity in pancreatic cancer and, furthermore, we have determined that the lack of SOD2 expression may result in a therapeutic advantage." (PMID 17895890, 2007). "We have recently shown that the sod2 promoter is hypermethylated in multiple myeloma, so we sought to determine if hypermethylation may be an explanation for the decreased expression of SOD2 observed in pancreatic carcinoma cell lines." (PMID 17895890, 2007). "Decreased expression of SOD2 has been noted, initially, in pancreatic carcinoma cells lines." (PMID 17895890, 2007). "To examine the more global consequences of SOD2 expression on the cellular processes of pancreatic carcinoma, we have employed a gestalt approach of examining how SOD2 affects vital processes of signal-transduction proteins, transcription factor activation, and gene regulation." (PMID 17895890, 2007).